RNU4-64P (RNA, U4 small nuclear 64, pseudogene)
Gene: Small nuclear RNA gene on chromosome 4 (186,026,456 to 186,026,586, reverse strand). Ensembl gene ENSG00000222727.
Homologues: Orthologues: chimpanzee U4 (98% identical), macaque U4 (89% identical), guinea pig U4 (55% identical), pig U4 (53% identical), dog U4 (53% identical). Paralogues in human: RNU4-28P (60% identical), RNU4-30P (59% identical), RNU4-9P (59% identical), RNU4-48P (57% identical), RNU4-84P (57% identical), RNU4-79P (56% identical), RNU4-82P (56% identical), RNU4-22P (56% identical), RNU4-55P (56% identical), RNU4-29P (55% identical), RNU4-77P (55% identical), RNU4-42P (54% identical), and 81 more.